CD27 (CD27 molecule)
Diseases named in the same sentence as CD27 in open-access papers (continued):
Sharing a sentence is not in itself a finding about the gene and the disease.
Sepsis (19 papers, 2016 to 2025). Sepsis is defined as life-threatening organ dysfunction caused by a dysregulated host response to infection. "The odds ratio (OR) analysis identified CD27 as having the highest odds ratio, highlighting its strong association with clinically overt sepsis and suggesting its critical role in the disease’s onset." (PMID 41472734, 2025). "The hazard ratio analysis reinforced CD27’s highest risk association, further linking it to clinically overt sepsis." (PMID 41472734, 2025). "A key finding of our present study in critically ill adult patients with sepsis was higher expression of PD-1/PD-L in the lymphocyte subsets associated with memory status, i.e. CD27+ B cells and CD27- CD4+ T cells." (PMID 29661225, 2018). "CD27 may help identify preterm infants with sepsis and may also help clinicians identify children at high risk." (PMID 39654893, 2024). "This analysis underscores the importance of multiple immunomodulatory proteins, particularly CD27, KLRB1, RETN, and CD163, in the risk of clinically overt sepsis, suggesting their potential as candidates for disease prognosis and treatment targets." (PMID 41472734, 2025). "The proportion of CD27+ activated CD4+ T cells was higher than in sepsis, while the CD56+ cytotoxic CD8+ T cell frequency was reduced." (PMID 35216673, 2022). "CD27, which is important in the generation of T-lymphocyte memory and viral immunity, was specifically downregulated in late sepsis activated CD8+ T-lymphocytes." (PMID 34484194, 2021). "The novel findings from this pilot study include the first report of higher B cell expression of PD-1, PD-L1 and PD-L2 in sepsis, and differential expression of PD-1 by CD27 status in both B and CD4+ T cells." (PMID 29661225, 2018). "Comparison of the expression levels as determined by percentage positivity of PD-1, PD-L1 and PD-L2 on B cell subsets (CD27+ and CD27-) in patients with sepsis and healthy controls." (PMID 29661225, 2018). "In patients with sepsis, expression of PD-1 was higher on CD27- T cells than CD27+ T cells, by both percentage positivity and MFI (70.45% vs 35.15%, p < 0.0001; 972 vs 716, p < 0.0001)." (PMID 29661225, 2018). "Comparison of the expression levels as determined by percentage positivity of PD-1, PD-L1 and PD-L2 on CD4+ T cell subsets (CD27+ and CD27-) between patients with sepsis and healthy controls." (PMID 29661225, 2018). "The proportion of B cells positive for PD-1 and the corresponding MFI were significantly greater in patients with sepsis than in controls (26.5% vs 8.8%, p = 0.0002; 483 vs 348, p = 0.0003): this was true of both CD27+ and CD27- subsets." (PMID 29661225, 2018). "Comparison of expression of PD-1, PD-L1 and PD-L2 as determined by MFI on CD4+ T cell subsets (CD27+ and CD27-) between patients with sepsis and healthy controls." (PMID 29661225, 2018). "Comparison of expression of PD-1, PD-L1 and PD-L2 as determined by MFI on B cell subsets (CD27+ and CD27-) in patients with sepsis and healthy controls." (PMID 29661225, 2018). "The percentage positivity of PD-L2 was higher in sepsis than controls in the CD27+ subset only (3.59% vs 0.41%, p = 0.0317)." (PMID 29661225, 2018). "By administration of lipopolysaccharides (LPS) in mice to mimic sepsis, we found that shortly after opening the blood–brain barrier, conventional CD11b+CD27+ NK subset migrated into the brain followed by subsequent neutrophil infiltration." (PMID 27270556, 2016). "In the early stages of sepsis, elevated CD27 expression may amplify the systemic inflammatory response by increasing pro-inflammatory cytokines such as IFN-γ." (PMID 41472734, 2025). "To determine whether sepsis severity influences the distribution of NK cell subpopulations—defined by CD11b and CD27 expression, which reflect maturation status and functional diversity—we analyzed their proportions in both MGS and HGS models." (PMID 41258565, 2025).
Sepsis (continued). "This multidimensional regulatory network may initially present a pro-inflammatory state (dominated by CD27/RETN) in early sepsis, transitioning to immunosuppression (upregulation of KLRB1/CD163) in later stages." (PMID 41472734, 2025). "Thus, balancing CD27 expression is crucial for managing the inflammatory response in sepsis patients." (PMID 41472734, 2025). "This is also consistent with a depletion of CD27+ B cells in blood in sepsis." (PMID 35251032, 2022). "PD-L2 expression on CD27+ B cells was also higher in patients with sepsis (p = 0.0317)." (PMID 29661225, 2018). "A reduction in naive B cells (CD19+CD27–), and an increase in immature B cells (CD19+CD5+CD27–CD21–/low) have been documented in elderly patients with sepsis." (PMID 41346634, 2025). "We identified and validated CD27, KLRB1, RETN, and CD163 as key biomarkers of sepsis by integrating transcriptome and single-cell data using bioinformatics and machine learning." (PMID 41472734, 2025). "In conclusion, our research revealed that CD27, KLRB1, RETN, and CD163 are highly specific and sensitive biomarkers for sepsis." (PMID 41472734, 2025). "Study showed some hub genes (CD2, CD27, GZMA, KLRB1, and PRF1) have been screened out as sepsis biomarkers and all of them were down regulated genes in sepsis, which consistent with our findings." (PMID 39654893, 2024). "Proportion of CD27+ B cells, CD27- B cells, CD27+ CD4+ T cells and CD27- CD4+ T cells that express PD-1, PD-L1 and PD-L2 in patients with sepsis compared to healthy controls." (PMID 29661225, 2018). "We therefore measured PD-1, PD-L1 and PD-L2 surface expression on CD27+ and CD27- subsets of CD4+ T and B lymphocytes using flow cytometry in adult patients with sepsis on the intensive care unit (ICU)." (PMID 29661225, 2018). "Based on this study’s findings and existing research theories, we propose that CD27, KLRB1, RETN, and CD163 may collaboratively regulate immune homeostasis in sepsis through their interactions." (PMID 41472734, 2025). "Further survival analysis revealed that while the expression levels of KLRB1, RETN, and CD163 significantly influenced sepsis prognosis, CD27 did not demonstrate statistical significance." (PMID 41472734, 2025). "Only activated T cells (CD19−CD3+CD27+) were significantly reduced in the peripheral blood of sepsis patients compared to healthy controls but not in surgery-only patients." (PMID 38984201, 2024). "Unlike BTLA and TIM-3, plasma levels of soluble CD27 are typically used as a marker of immune activation and currently has not been studied for its role in infection (i.e., sepsis) or burn injuries." (PMID 35958579, 2022). "Another rationale for assessing CD27-based memory lymphocyte subsets is the selective depletion of memory B cells in sepsis; it is not known whether PD-1 expression varies by lymphocyte memory status." (PMID 29661225, 2018). "Expression levels of PD-1, PD-L1 and PD-L2 on four lymphocyte subsets (CD27 + CD19+ B cells, CD27-CD19+ B cells, CD27 + CD4+ T cells and CD27-CD4+ T cells) were compared between 22 patients with sepsis (including 11 survivors and 11 non-survivors) and 11 healthy controls using flow cytometry." (PMID 29661225, 2018).
B cell lymphoma (16 papers, 2013 to 2025). "B-cell NHLs frequently express CD27/CD27L (TNFRSF7/TNFSF7), CD30 or CD30L (TNFRSF8 or TNFSF8), CD40 (TNFRSF5), and TNFRs/TNF positive (TNFRSF1 and 2/TNFSF2), but T-cell NHLs show expression of CD30, CD40L (TNFSF5), and TNFRs/TNF." (PMID 37240076, 2023). "CD27 activates protein kinase C (PKC) and induces cellular proliferation in B-cell lymphomas and anti-CD27 mAb shows antitumor activity." (PMID 34696358, 2021). "Like CD27‐, CD70‐deficient patients, RASGRP1‐deficient patients appear to be particularly prone to develop EBV‐driven B‐cell lymphoma as the four patients described today had Hodgkin lymphoma." (PMID 29282224, 2018). "Additionally, many B-cell lymphomas express CD27, which may serve as a direct target in a fashion similar to CD20 targeting with Rituximab." (PMID 34630390, 2021). "In addition to combination with checkpoint inhibitor therapy, the combination of anti-CD20 and CD27 agonizing monoclonal antibodies has been investigated in an immunocompetent murine B-cell lymphoma and B-chronic lymphocytic leukemia models with a 100% tumor remission rate noted at 100 days." (PMID 34630390, 2021). "Apart from CD27 signaling, CD70 reverse signaling was also reported to increase proliferation in a low-grade B cell lymphoma." (PMID 34991665, 2022). "One of the strengths of our WM scoring system is that it relies on antigen markers that are routinely used and widely available in haematology laboratories performing MFC analysis for B‐cell lymphomas (CD19, CD79b, CD22, FMC7 and CD27) and myeloid neoplasms (CD13)." (PMID 40407640, 2025). "These investigations demonstrate that agonistic anti-CD27 can improve the anti-tumor efficacy of a tumor-targeting mAb to B cell lymphoma in a way not seen with other immunomodulatory mAbs." (PMID 29198913, 2017).
HIV-1 infection (16 papers, 2004 to 2025). The type species of lentivirus and the etiologic agent of acquired immunodeficiency syndrome (AIDS). "The increased levels of the three phospho-proteins during HIV-1 infection were observed across all memory subsets that are determined by differential expression of CD27 and CCR7 markers." (PMID 31658294, 2019). "In this respect, it is possible that the co-expression of IgD and IgG/IgA by CD27− B cells during HIV-1 infection is increased." (PMID 19412542, 2009). "We have recently shown that during chronic HIV-1 infection, CD27+ and CD27− B-cells show an altered migration patterns due to alterations in expression of the receptor-ligand pair CXCR5/CXCL13." (PMID 19412542, 2009). "During HIV-1 infection the B-cell compartment displays several alterations; naïve B-cells, which normally lack CD27 expression, have an altered expression of several differentiation markers and hypergammaglobulinemia is frequently observed." (PMID 19412542, 2009). "Taken together, these results show that during HIV-1 infection, CD27− B-cells can also produce class switched and somatically hypermutated antibodies." (PMID 19412542, 2009). "Increased proportions of CD28−/CD27+ CD8+ T-cells during acute HIV-1 infection are likely to reflect expansion of HIV-specific CD8+ T-cells." (PMID 14966528, 2004). "No changes were observed in the frequency of naïve B cells (CD21+CD27-) following HIV-1 infection." (PMID 28943879, 2017). "Our results on AID expression and the lack of correlation to the memory B-cell population in HIV-1 infected individuals may suggest that CD27− B-cells participate in the production of class switched Abs during HIV-1 infection." (PMID 19412542, 2009). "To define PB kinetics in HIV-1 infection, we assessed the frequencies of CD3−CD19+CD27+CD38+++ cells before and upon HIV-1 infection." (PMID 28943879, 2017). "We characterized the profile of CD4+ T cells most permissive to productive HIV-1 infection by staining for CD45RO, CD27 and HSA." (PMID 22876188, 2012). "Here, we used polychromatic flow cytometry to examine the co-expression of CD38, CD27 and CD28 on total T cells and antigen-specific (HIV, CMV) T cells in a cohort of adults in early HIV-1 infection (within 6 months of acquisition)." (PMID 19198651, 2009). "We thus propose a model where CD27− B-cells are more prone to respond to unspecific signals such as polyclonal bystander activation and TLR triggering by microbial products during HIV-1 infection." (PMID 19412542, 2009). "It has been shown that PD-1 expression was increased on CD21+ CD27+ resting memory B cells in HIV-1-infected patients, which might contribute to a decreased ratio of the resting memory B cells during HIV-1 infection." (PMID 32256500, 2020). "Activated human memory B cells, defined as CD20+/CD21lo/CD27+, and tissue-like memory B cells, defined as CD20+/CD21lo/CD27−, are increased during persistent HIV-1 infection, whereas resting memory B cells, defined as CD20+/CD21hi/CD27+, are decreased in frequency." (PMID 28928737, 2017). "In primary and chronic untreated HIV-1 infection (PHI and CHI), prior studies, largely cross-sectional in nature, have shown that B cell subset frequencies, defined by surface expression levels of CD21 and CD27, are disrupted." (PMID 28943879, 2017). "In this scenario, the lack of specific immune responses during HIV-1 infection would be due both to the involvement of CD27− B-cells in CSR and SHM, triggered by unspecific stimuli, and to CD27+ B-cell exhaustion." (PMID 19412542, 2009). "Finally, including CD19+ IgD+ IgM+ CD27+ B cell populations in our analyses did not alter our conclusion that acute HIV-1 infection results in increased percentages of memory cells in blood or gut (unpublished data)." (PMID 19582166, 2009).
HIV-1 infection (continued). "It has been reported that Tim-3-expressing CD8+ T cells during HCV or HIV-1 infection display either dominant CCR7+ central memory or CCR7+ and/or CD27+ phenotype profiles with no or low expression of effector surrogate marker CD127." (PMID 23144609, 2012).
multiple sclerosis (16 papers, 2009 to 2025). A progressive autoimmune disorder affecting the central nervous system resulting in demyelination. "In this study, we investigate relevant immune and neuro-pathological features of soluble CD27 in multiple sclerosis." (PMID 38609999, 2024). "In a study including matched cerebrospinal fluid and post-mortem brain tissues of patients with multiple sclerosis and control cases, levels of soluble CD27 were correlated with perivascular and meningeal infiltrates and with neuropathological features." (PMID 38609999, 2024). "Eight markers were found to be significantly differently expressed in CSF of multiple sclerosis versus control cases: chitinase-3-like-1, soluble CD27 (sCD27), neurofilament light, osteopontin, C5, iC3b, C9 and TCC." (PMID 38368354, 2024). "In these healthy controls, we found that the multiple sclerosis risk allele rs9282641*G is associated with a higher percentage of CD86-positive B cells, primarily in naïve B cells (CD19+CD27−) (P = 5.38 × 10−5)." (PMID 29361022, 2018). "CD27 is a T-cell activation marker, whose soluble form has been shown by others to be significantly elevated in people with multiple sclerosis, and predictive of future multiple sclerosis disease activity, including transition from CIS to multiple sclerosis." (PMID 38368354, 2024). "Soluble CD27 is a promising cerebrospinal fluid inflammatory biomarker in multiple sclerosis." (PMID 38609999, 2024). "These associations are confirmed in multiple sclerosis patients, where associations were observed in three of six cell types, i.e. total B cells (CD19+), naïve B cells (CD19+CD27−) and class-switched memory B cells (CD19+CD27+IgD−) (P ≤ 0.048)." (PMID 29361022, 2018).
glioma (14 papers, 2015 to 2025). A benign or malignant brain and spinal cord tumor that arises from glial cells (astrocytes, oligodendrocytes, ependymal cells). "CD70 is a receptor that is overexpressed in glial tumor cells associated with poor survival, which binds CD27." (PMID 37830595, 2023). "In terms of B cells, we observed that CD27 on CD24+ CD27+ B cell and CD27 on unswitched memory B cell were positively correlated with glioma risk, suggesting that CD27 on B cell might play a role in tumor development." (PMID 40657381, 2025). "Specifically, a decline in the maturation of CD27+/CD11b+ natural killer (NK) cells was observed, accompanied by accelerated glioma progression." (PMID 41516317, 2025). "Upregulation of some immune checkpoints, such as CD27, CD274 (PD-L1), CTLA4, IDO1, and PDCD1 (PD-1), were reported to be associated with poor survival and recurrence in gliomas." (PMID 35874989, 2022). "Varlilumab, an CD27 agonist, is now being administered in ongoing clinical trials for several cancers, including gliomas." (PMID 35029050, 2022). "For instance, the association between memory B cells (CD27+ CD24+ B cells) and increased glioma risk aligns with recent studies suggesting that memory B cells may contribute to tumor progression by promoting an immunosuppressive microenvironment 50,53." (PMID 40657381, 2025). "Additionally, antibiotic-induced dysbiosis was shown to accelerate glioma progression, due to impaired innate anti-tumour immunity, characterized by the disrupted maturation of CD27+/CD11b+ NK cells." (PMID 41516317, 2025). "In vivo studies on murine glioma models indicate that CD70-targeted therapies can cause tumor regression, but contrasting evidence suggests that the CD27 pathway might also suppress T lymphocytes." (PMID 38342925, 2024). "This further broadens the utility of CD70/CD27 axis blockade, and a CD70‐specific CAR T cell strategy has also recently been tested for gliomas." (PMID 36471481, 2022). "Rad_score was positively correlated with glioma‐related genes, such as PDCD1, CD27, and CD70." (PMID 39030882, 2024). "Moreover, the high/low radiomics scores were highly correlated with the known glioma‐related genes, including CD70, CD27, and PDCD1." (PMID 39030882, 2024). "Additionally, while outside the scope of this review focusing on immunotherapies for high-grade gliomas, a recent pilot study evaluating the safety and immunogenicity of IMA950/poly-ICLC combined with the agonistic anti-CD27 antibody varlilumab in low-grade gliomas is worth noting." (PMID 40507329, 2025). "In addition, we found that cell-to-cell contacting with patient-derived CD57+ glioma cells induced rapid upregulation of CD57 on activated CD8+ T cells, independent of antigen recognition and without concomitant loss of CD28 or CD27." (PMID 25426558, 2015).
Immunodeficiency (13 papers, 2016 to 2024). Failure of the immune system to protect the body adequately from infection, due to the absence or insufficiency of some component process or substance. "Naive wild-type (WT), Fcgr3−/− (FcγRIII−/−) or SCID (severe combined immune deficiency) mice were treated with a single dose of anti-CD27, and the expression of the activation marker, KLRG1, was monitored on peripheral blood NK cells." (PMID 29198913, 2017). "Our results suggest that ASC are altered in immune-mediated pathology but are exploratory and further research is needed to unravel the role of CD27- ASC in immune disorders." (PMID 37492569, 2023). "Our extensive analysis confirmed, on a pediatric cohort, that the increase of CD21– CD27– B cells percentage is mainly correlated to immunodeficiencies, autoimmune, inflammatory, and hematological diseases, as previously reported on adult populations." (PMID 35722474, 2022). "Several immunodeficiency disorders associated with EBV lymphoproliferation have been described, including deficiency of ITK, XIAP, STK4, SH2D1A, and CD27." (PMID 27338827, 2016). "The soluble 32-kD form of CD27 (sCD27), which can be found in body fluids such as plasma and cerebrospinal fluid (CSF), has the potential to serve as a biomarker for diseases involving immune dysfunction and/or activation." (PMID 38883839, 2024). "Soluble CD27 (sCD27) is a potential biomarker for diseases involving immune dysfunction." (PMID 38883839, 2024). "In humans with RelB deficiency, patients suffer from severe immunodeficiency with shortage-specific antibodies due to the halted B cell development and the absent CD27+ memory B cells." (PMID 34521820, 2021). "Additional studies are needed to unravel the role of CD27- ASC in health and immune disorders." (PMID 37492569, 2023).